CLIC1 (CLIC family member 1)
Diseases named in the same sentence as CLIC1 in open-access papers (continued):
Sharing a sentence is not in itself a finding about the gene and the disease.
Cognitive impairment (2 papers, 2020 to 2026). Abnormal cognition is characterized by deficits in thinking, reasoning, or remembering. "Our analyses show that significantly higher levels of CLIC1 exist in AD patients compared with cognitive normal and mild cognitive impairment groups and the effect size of the difference in moderate to high." (PMID 32604772, 2020).
cystic fibrosis (2 papers, 2018 to 2021). Autosomal recessive disorder caused by pathogenic variants in the CFTR gene (cystic fibrosis transmembrane conductance regulator), which encodes a chloride and bicarbonate channel expressed in epithelial cells, and follow the diagnosis criteria. "The authors concluded that manipulating CLIC1 properties may enhance Cl- conductance, thus proposing the possibility to potentiate CLIC1 functional activity as a possible therapeutic strategy in conditions of impaired chloride homeostasis as cystic fibrosis." (PMID 34357102, 2021). "Our data suggest it is possible that manipulating CLIC1 could be a way to further enhance Cl− channel activity and that this could therefore prove a novel therapeutic approach to aid in the treatment of conditions where chloride homeostasis is impacted such as cystic fibrosis." (PMID 29368798, 2018).
depression (2 papers, 2022 to 2023). "Therefore, we tested whether ablation of Clic1 had any overt effects on depression or anxiety-like behavior in mice." (PMID 37604246, 2023). "A history of clinical depression in PD was also related to a second DMR in chromosome 6 in the MHC class III region, near cg21769117, the CpG in the CLIC1 gene." (PMID 36325427, 2022). "Clic1 KO mice performed in a similar way to WT mice in all three behavioral assays, elevated plus maze, marble burying assays and forced-swim tests, suggesting Clic1 ablation had no overt effect on depression, compulsive behavior and anxiety." (PMID 37604246, 2023).
diabetes (2 papers, 2024). "Building upon the recognition of salivary CLIC1 as a diagnostic biomarker and considering its clinical verification, it was observed that salivary CLIC1 levels were significantly elevated in the periodontitis patient group and notably higher in the group with periodontitis associated with diabetes." (PMID 38327933, 2024). "This proves that the concentration of salivary CLIC1 consistently increases from a healthy state in periodontitis individuals and is even higher in periodontitis with diabetes mellitus patients." (PMID 38327933, 2024). "The mean level of CLIC1 (ng/ml) in the healthy group was 0.901; the level in the periodontitis group was 1.436; and the level in the periodontitis with diabetes mellitus group was 1.617." (PMID 38327933, 2024). "According to the results of the current study, group 3, which includes people with periodontitis and diabetes, had a significantly higher mean CLIC1 concentration than group 2, which includes systemically healthy individuals." (PMID 38327933, 2024). "This implies that the mean concentration of CLIC1 rises with disease severity, particularly in patients with systemic comorbidities like diabetes mellitus." (PMID 38327933, 2024). "Specifically in β-cells, TG-induced stress resulted in increased expression of ARID5B (part of demethylase complex), MAP1LC3A (Mitophagy), and CLIC1 (chloride channel) expression and decreased G6PC2 and HADH, which have been associated with diabetes." (PMID 38956087, 2024). "CLIC1 concentrations were positively correlated with periodontitis in individuals with diabetes." (PMID 38327933, 2024). "Chloride intracellular channel 1 (CLIC1) was identified as a hub gene linking the pathogenesis of periodontitis and diabetes mellitus using a bioinformatic tool." (PMID 38327933, 2024).
laryngeal carcinoma (2 papers, 2013 to 2022). Carcinoma that arises from the laryngeal epithelium. "Proteomic analysis of the laryngeal cancer cell line HEp-2 and the radiation-resistant cell line HEp-2-RR showed that Chloride Intracellular Channel 1 (CLIC1) induces radiation resistance by inhibiting the production of reactive oxygen species." (PMID 35280744, 2022). "This is suggested by the notion that intracellular Cl− channel CLIC1 protein expression regulates radiosensitivity in laryngeal cancer cells." (PMID 23966948, 2013).
Salmonella Infections (2 papers, 2017 to 2021). Infections with bacteria of the genus SALMONELLA. "Some of them, such as tyrosine-protein phosphatase non-receptor type 1 (PTPN1), serum amyloid A-1 protein (SAA1) and chloride intracellular channel protein 1 (CLIC1), although previously reported in Salmonella infections, we have for the first time clearly associated them with SPI-2 effectors." (PMID 34461813, 2021).
viral infection (2 papers, 2019 to 2024). "Interestingly, IAV-PR8 infection activated apoptosis and necrosis pathways in CLIC1 KD cells, showing that CLIC1 may be involved in viral infection-mediated apoptosis and necrosis pathway activation." (PMID 38257829, 2024). "We focused on CLIC1 and CLIC4 as candidate channels, due to their known sensitivity to DIDS, 9-ACA and NPPB and involvement in other virus infections such as hepatitis C virus and Merkel cell polyomavirus." (PMID 31483794, 2019).
acute pancreatitis (1 paper, 2017). An acute inflammatory process that leads to necrosis of the pancreatic parenchyma. "mRNA encoding CLIC1 was upregulated 10.3‐fold during acute pancreatitis in the wild‐type mice and was undetectable in the C1KO mice." (PMID 28275112, 2017). "In summary, in this model of acute pancreatitis, CLIC1 is dramatically upregulated at the level of RNA and protein in the pancreas following acute injury, with increased protein abundance most prominent in the pancreatic duct cells but detectable increase in acinar cells as well." (PMID 28275112, 2017).
atherosclerosis (1 paper, 2025). A disease characterized by the build-up of fatty material and calcium deposition in the arterial wall resulting in partial or complete occlusion of the arterial lumen. "The similarities pathogenesis between KD and atherosclerosis suggests a potential role for CLIC1 in KD." (PMID 40276515, 2025).
Bestrophinopathy (1 paper, 2017). "We found the same dialysis activated Cl- currents in bone marrow derived neutrophils from CLIC1, CLCN3, CLCN7 and KCC3 KO animals and in blood neutrophils from a Bestrophinopathy patient (Best1 H178P) (representative current traces)." (PMID 28553230, 2017).
celiac disease (1 paper, 2022). An autoimmune genetic disorder with an unknown pattern of inheritance that primarily affects the digestive tract. "Upregulation of CLIC1 in females was significantly associated with type 1 diabetes (NCases = 230) and celiac disease (NCases = 53) (Females-Spleen-CLIC1, p < 1.49 × 10−9)." (PMID 35379376, 2022). "These associations are driven in part by the MHC-gene CLIC1; predicted upregulation of CLIC1 in spleen was associated with celiac disease and type 1 diabetes (p = 1.30 × 10−11, p = 5.08 × 10−20, respectively) in the overall cohort." (PMID 35379376, 2022). "We found a sex-specific association of CLIC1-GReX with celiac disease in females, indicating sex-specific regulation of AN-genes may be contributing to the disparity in autoimmune diagnoses and symptomatology between the sexes." (PMID 35379376, 2022).
cholangiocarcinoma (1 paper, 2021). A carcinoma that arises from the intrahepatic biliary tree (intrahepatic cholangiocarcinoma) or from the junction, or adjacent to the junction, of the right and left hepatic ducts (hilar cholangiocarcinoma). "In cholangiocarcinoma, UCA1 upregulates chloride intracellular channel 1 (CLIC1) expression by inhibiting miR-122 expression and activating the ERK/MAPK signaling pathway to promote the metastasis of malignant cells." (PMID 33777227, 2021).
choriocarcinoma (1 paper, 2021). An aggressive malignant tumor arising from trophoblastic cells. "However, Wu J. and Wang D. showed a role of CLIC1 in inducing drug resistance in human choriocarcinoma by positive regulation of MRP1." (PMID 35054564, 2021). "Despite a smaller amount of research, CLIC1 might induce drug resistance in human choriocarcinoma by positive regulation of MRP1." (PMID 35054564, 2021). "We might presume that CLIC1 exerts its chemoresistant property by promoting the expression of MRP1 in choriocarcinoma." (PMID 35054564, 2021).
cocaine addiction (1 paper, 2025). "CALM3 and JUN were downregulated in the cocaine addiction group compared to controls (p < 0.05), whereas CCL2, CD44, CLIC1, and VCAM1 were upregulated (p < 0.05)." (PMID 41465087, 2025).
colon adenocarcinoma (1 paper, 2019). "In fact, the inhibition of CLIC1 channel activity by the CLIC ion channel blocker IAA94 reduces intracellular ROS production during hypoxia-reoxygenation treatment in LOVO cells, human colon adenocarcinoma cells, suggesting that CLIC1 sustains ROS levels." (PMID 31316050, 2019).
colorectal adenocarcinoma (1 paper, 2023). The most common type of colorectal carcinoma. "A CLIC1 score of 3 was found in 50% of the colorectal adenocarcinomas, with a score of 2 being found for the other half." (PMID 36826036, 2023).
dementia (1 paper, 2020). Loss of intellectual abilities interfering with an individual's social and occupational functions. "Although we identified one significant probe in CLIC1, CLIC1 levels alone were not sufficient to predict dementia status and cannot be used alone in a clinical setting." (PMID 32604772, 2020).
eating disorder (1 paper, 2023). A broad group of psychological disorders with abnormal eating behaviors leading to physiological effects from overeating or insufficient food intake. "To further explore the role of Clic1 in food intake in broader translation models of eating disorders, we tested whether IAA94 treatment impacted binge-eating in mice." (PMID 37604246, 2023).
endothelial dysfunction (1 paper, 2016). In vascular diseases, endothelial dysfunction is a systemic pathological state of the endothelium (the inner lining of blood vessels) and can be broadly defined as an imbalance between vasodilating and vasoconstricting substances produced by (or acting on) the endothelium. "Furthermore, we investigated the relationship between CLIC1 and endothelial dysfunction as the earliest event in atherogenesis." (PMID 27861612, 2016). "Considering that CLIC1 is a novel metamorphic protein involved in the regulation of oxidative stress responses and inflammation, we investigated its role in AS, whose insertion into the membrane to form active ion channel alteration could lead to endothelial dysfunction." (PMID 27861612, 2016).
epilepsy (1 paper, 2024). A brain disorder characterized by episodes of abnormally increased neuronal discharge resulting in transient episodes of sensory or motor neurological dysfunction, or psychic dysfunction. "The CFA14 risk haplotype was associated with upregulation of CLIC1, ACE2, and PIGN and downregulation of EPDR1, all known to be involved with epilepsy or the Wnt/β-catenin signaling pathway." (PMID 39596674, 2024).
experimental autoimmune encephalomyelitis (1 paper, 2016). An autoimmune demyelinating disease of the central nervous system that is produced experimentally in animals by the injection of homogenized brain or spinal cord in Freund's adjuvant. "CLIC1−/− BMDC displayed reduced in vitro antigen processing and presentation of full-length myelin oligodendrocyte glycoprotein (MOG) and reduced MOG-induced experimental autoimmune encephalomyelitis." (PMID 27113959, 2016).
gastric tumors (1 paper, 2025). "Conversely, circ_0008287, which is overexpressed in gastric tumors, promotes immune evasion by sponging miR-548c-3p to derepress chloride intracellular channel 1 (CLIC1)." (PMID 41229433, 2025).
glomerulonephritis (1 paper, 2021). A renal disorder characterized by damage in the glomeruli. "scRNA sequencing results of specimens from patients undergoing kidney transplantation, or patients with glomerulonephritis, malignant renal tumors, or chronic interstitial nephritis, revealed that the gene expression of chloride intracellular channel 1 (Clic1) was up-regulated." (PMID 35059392, 2021).
heart failure (1 paper, 2026). Inability of the heart to pump blood at an adequate rate to meet tissue metabolic requirements. "We used single‐cell RNA‐seq to demonstrate the significant upregulation of CLIC1, CLIC4, and CLIC5 in a TAC mouse model and patients with DCM, underscoring their conserved roles in heart failure progression." (PMID 41521401, 2026). "Among CLICs, CLIC1, CLIC4, and CLIC5 were significantly upregulated during the hypertrophic and heart failure phases of the TAC mouse model." (PMID 41521401, 2026). "Previous studies have reported the involvement of CLICs (CLIC1, CLIC4, and CLIC5) in AF, suggesting that these channels play a broader role in atrial remodeling beyond heart failure." (PMID 41521401, 2026).
heart valvular diseases (1 paper, 2017). "The alterations of the chloride channels including CLIC1, CLIC4, and CLIC5 occur in both RNA-Seq and iTRAQ studies strongly support that the changes of chloride channels may play an important role in the pathophysiology of AF at least in heart valvular diseases." (PMID 28860555, 2017).
hydatidiform mole (1 paper, 2019). A gestational trophoblastic disorder characterized by marked enlargement of the chorionic villi, hyperplasia of the villous trophoblastic cells and hydropic changes. "Thus, the research showed CLIC1 to be a potential new prognostic biomarker that may indicate patients with hydatidiform moles that are at risk of malignant transformation." (PMID 30744112, 2019). "Among them, chloride intracellular channel protein 1 (CLIC1) was selected by the authors of the 2011 study for further investigation, with results indicating that the levels of CLIC1 expression in choriocarcinoma tissue were higher than in complete hydatidiform mole tissue." (PMID 30744112, 2019).
Hypoglycemia (1 paper, 2022). A decreased concentration of glucose in the blood. "Upregulation of CLIC1 was associated with glucagon, a hormone used to treat severe hypoglycemia, in the overall cohort (NCases = 129) (Overall-Spleen-CLIC1, p = 4.20 × 10−9) and in females (NCases = 78) (Females-Spleen-CLIC1, p = 1.4 × 10−8)." (PMID 35379376, 2022).
IgA nephropathy (1 paper, 2021). "Compared with the mesangial of donor, the gene CLIC1 and RPS26 were up‐regulated in mesangial of IgA nephropathy(IgAN), whereas the gene JUNB was up‐regulated in podocyte of IgAN in comparison with that of donor." (PMID 33754492, 2021).
ischemic stroke (1 paper, 2025). A stroke disorder caused by obstruction of blood flow to the brain, due to thrombotic (local blood clot formation) or embolic (due to a blood clot or other material traveling from another site) event. "Although there are no specific studies directly focusing on CLIC1 inhibitors for CIRI, previous studies have suggested CLIC1 as a potential therapeutic target for central nervous system diseases, such as neurodegenerative diseases and ischemic stroke." (PMID 40966238, 2025).
lymphoblastic leukemia (1 paper, 2023). "Additionally, CLIC1 may have implications in lymphoblastic leukemia." (PMID 38027011, 2023).
mucinous tumors (1 paper, 2018). "Individually, CLIC1 or CLIC4 stained larger percentages of malignant tumors across all EOC subtypes compared with CA125, particularly early stage and mucinous tumors." (PMID 30282979, 2018). "Finally, CA125, but not CLIC1 or CLIC4, showed a significant tumor subtype bias primarily because the mucinous tumors did not stain with CA125." (PMID 30282979, 2018).
multiple sclerosis (1 paper, 2023). A progressive autoimmune disorder affecting the central nervous system resulting in demyelination. "Finally, astrocyte cluster 8 (MMP7, SERPINA3, GZMA, and CLIC1) and microglial cluster 2 (DSG2 and TNFRSF25) were elevated in multiple sclerosis patients and suggested the pathogenic role of these biomarkers during multiple sclerosis progression." (PMID 37468977, 2023).
Myocardial fibrosis (1 paper, 2026). "In the present study, the upregulation of CLIC1 and CLIC4 in the TAC model and patients with DCM underscores their conserved role in myocardial fibrosis." (PMID 41521401, 2026).
Obesity (1 paper, 2023). Accumulation of substantial excess body fat. "In summary, we have identified hypothalamic expression of Clic1 plays a key role in food intake, providing a novel therapeutic target to treat overconsumption that is the root cause of modern obesity." (PMID 37604246, 2023). "It is also likely that the chronic inflammatory state associated with obesity plays a role in stimulating the persistent increase in membranal localization of Clic1." (PMID 37604246, 2023). "To test whether Clic1 inhibition could reduce food intake and induce weight loss in the context of obesity, we administered IAA94 to diet-induced obese mice." (PMID 37604246, 2023). "To explore the broader potential of Clic1 inhibition in genetic models of obesity, we tested the effect of IAA94 in the Magel2 KO mouse model of Prader–Willi syndrome." (PMID 37604246, 2023). "We studied the impact of Clic1 inhibition in mouse models of binge-eating, diet-induced obese mice and genetic models of obesity (Magel2 KO mice)." (PMID 37604246, 2023). "Next, we determined if chronic obesity impacts Clic1 cellular localization, by studying hypothalamic samples from lean and obese mice." (PMID 37604246, 2023). "In these studies, we investigate the role of Clic1 in food intake, weight gain and the investigate the impact of Clic1 inhibition as a potential treatment for obesity and metabolic health." (PMID 37604246, 2023). "These differentially expressed genes represent potential molecular targets downstream of Clic1 that could also be therapeutic targets for modulation of food intake in obesity." (PMID 37604246, 2023).
oral cancer (1 paper, 2025). "Prior research has provided evidence indicating that CLIC1 plays a crucial role in the advancement of various malignant tumors.There was a notable increase in CLIC1 expression observed in oral cancer tissues and in the blood of cancer patients." (PMID 40948771, 2025).
ovarian tumor (1 paper, 2018). "We previously showed, using a mouse xenograft model, that two members of the chloride intracellular channel (CLIC) protein family, CLIC1 and CLIC4, were produced in xenografted mice by implanted human ovarian tumor cells and shed into the blood." (PMID 30282979, 2018). "Meta-analysis of gene expression levels showed that the mRNA levels of CLIC1 and CLIC4 in normal ovarian surface epithelium, fallopian tube epithelium and ovarian tumors were consistent with the IHC staining patterns." (PMID 30282979, 2018).
pancreatic adenocarcinoma (1 paper, 2023). "In our study, except one case of pancreatic adenocarcinoma, all of the primary tumors were CLIC1-positive." (PMID 36826036, 2023).
periodontal disease (1 paper, 2024). "Within the confines of the study, it is possible to draw the conclusion that CLIC1 is a neoteric biomarker for detecting periodontal disease." (PMID 38327933, 2024).
periodontitis (1 paper, 2024). An acute or chronic inflammatory process that affects the tissues that surround and support the teeth. "Since we found elevated levels of salivary CLIC1 in periodontitis, our results are consistent with earlier research on chronic inflammatory states." (PMID 38327933, 2024). "Therefore, CLIC1 could be a diagnostic biomarker for patients with periodontitis." (PMID 38327933, 2024). "The objective of the present investigation is to ascertain how CLIC1 affects people with and without systemic disease who have periodontitis." (PMID 38327933, 2024).
Sepsis (1 paper, 2022). Sepsis is defined as life-threatening organ dysfunction caused by a dysregulated host response to infection. "CLIC1, UFD1, SEPT9, and UBE2A are new biomarkers found by us through the random forest model, and there is no research report related to sepsis so far." (PMID 35345523, 2022).